ROBO1 (roundabout guidance receptor 1)
Description:
Receptor for SLIT1 and SLIT2 that mediates cellular responses to molecular guidance cues in cellular migration, including axonal navigation at the ventral midline of the neural tube and projection of axons to different regions during neuronal development. Interaction with the intracellular domain of FLRT3 mediates axon attraction towards cells expressing NTN1. In axon growth cones, the silencing of the attractive effect of NTN1 by SLIT2 may require the formation of a ROBO1-DCC complex (By similarity). Plays a role in the regulation of cell migration via its interaction with MYO9B; inhibits MYO9B-mediated stimulation of RHOA GTPase activity, and thereby leads to increased levels of active, GTP-bound RHOA. May be required for lung development (By similarity).
Synonyms: DUTT1; FLJ21882; SAX3; CPHD8; NORS; NYS8
Tractability: Antibody: UniProt places it where antibodies can reach, with high confidence; its Gene Ontology location is reachable by antibodies, with high confidence; UniProt predicts a signal peptide or a membrane-spanning region; the Human Protein Atlas places it where antibodies can reach. PROTAC: UniProt records ubiquitination sites on it; ubiquitination databases record sites on it; its protein half-life has been measured.
Gene: Protein-coding gene on chromosome 3 (78,597,239 to 79,767,998, reverse strand). Ensembl gene ENSG00000169855.
Subcellular location: Cell membrane; Cell projection, axon; Endoplasmic reticulum-Golgi intermediate compartment membrane
Subcellular location (Human Protein Atlas): Plasma membrane; Primary cilium
Pathways (Reactome):
Developmental Biology: Activation of RAC1; Inactivation of CDC42 and RAC1; Netrin-1 signaling; Regulation of commissural axon pathfinding by SLIT and ROBO; Regulation of cortical dendrite branching; Regulation of expression of SLITs and ROBOs; Role of ABL in ROBO-SLIT signaling; SLIT2:ROBO1 increases RHOA activity; Signaling by ROBO receptors
Gene Ontology:
Molecular function: axon guidance receptor activity; identical protein binding; LRR domain binding; protein binding
Biological process: cell migration involved in sprouting angiogenesis; chemorepulsion involved in postnatal olfactory bulb interneuron migration; homophilic cell-cell adhesion; negative regulation of cell migration; negative regulation of chemokine-mediated signaling pathway; negative regulation of mammary gland epithelial cell proliferation; negative regulation of negative chemotaxis; positive regulation of axonogenesis; positive regulation of MAPK cascade; positive regulation of Rho protein signal transduction; positive regulation of vascular endothelial growth factor receptor signaling pathway; positive regulation of vascular endothelial growth factor signaling pathway; Roundabout signaling pathway; aorta development; aortic valve morphogenesis; axon midline choice point recognition; cell adhesion; endocardial cushion formation; heart induction; negative regulation of gene expression; nervous system development; outflow tract septum morphogenesis; positive regulation of gene expression; positive regulation of Notch signaling pathway; pulmonary valve morphogenesis; and 4 more
Cellular component: cell surface; cytoplasm; plasma membrane; endoplasmic reticulum-Golgi intermediate compartment membrane; axon
Genetic constraint (gnomAD): Loss-of-function variants: 126 observed, 170.6 expected, observed/expected ratio (o/e) 0.74, 90% interval 0.64 to 0.86. The upper end of that interval is the gene's LOEUF score, 0.86, which puts it in group 3 of 6, group 1 being the genes least tolerant of losing a copy. Missense variants: 1,815 observed, 2,007.5 expected, observed/expected ratio (o/e) 0.9, 90% interval 0.87 to 0.94. Synonymous variants: 780 observed, 715.05 expected, observed/expected ratio (o/e) 1.09, 90% interval 1.03 to 1.16.
Gene-disease validity (ClinGen):
ClinGen rates the evidence that ROBO1 causes each of these diseases.
congenital heart disease (autosomal dominant; autosomal recessive): Limited. A heart disease that is present at birth.
Homologues: Orthologues: chimpanzee ROBO1 (98% identical), pig ROBO1 (97% identical), macaque ROBO1 (97% identical), rabbit ROBO1 (97% identical), guinea pig ROBO1 (94% identical), mouse Robo1 (93% identical), rat Robo1 (91% identical), tropical clawed frog robo1 (85% identical), zebrafish robo1 (70% identical). Paralogues in human: ROBO2 (48% identical), ROBO3 (37% identical), SDK2 (17% identical), SDK1 (17% identical), NEO1 (16% identical), DCC (16% identical), HMCN2 (16% identical), IGSF10 (15% identical), MXRA5 (15% identical), NRCAM (15% identical), PRTG (15% identical), CNTN4 (15% identical), and 24 more.
Diseases named in the same sentence as ROBO1 in open-access papers:
ROBO1 is named in the same sentence as 187 diseases in open-access papers, as found by Europe PMC text mining. Sharing a sentence is not in itself a finding about the gene and the disease. The quoted sentences say what the papers report.
breast carcinoma (41 papers, 2004 to 2025). "ROBO1 expression was negatively associated with prognosis for PCa risk/metastasis, breast cancer, and colorectal cancer." (PMID 33540941, 2021). "Prior work showing high Robo1 expression association with good outcome in breast cancer is consistent with our finding." (PMID 32766238, 2020). "The loss of SLIT2, SLIT3, or ROBO1 protein in mouse breast cancer models results in an increase in repair processes in tissues, promoting cell proliferation." (PMID 29743814, 2018). "Slit2 overexpressing breast cancer cells displayed the reduced tumor growth and Slit2 or Robo1-deficient mammary epithelium led to hyperplasia after xenografts transplantation." (PMID 26400100, 2015). "Expressions of SLIT2 and ROBO1 are downregulated in ductal carcinoma in situ and invasive breast cancer tissues, and such downregulation is associated with poor prognosis and brain metastasis of breast cancer." (PMID 35053460, 2022). "Although Slit2/Robo1 is linked to aberrant growth and migration of tumor epithelial cells, which consequently resulted in metastatic spread of cancer cells, the clinical significance of this axis in brain metastasis of breast cancer is unknown." (PMID 26400100, 2015). "SLITs and ROBOs have been implicated in development of both the normal mammary gland and breast cancer and ROBO1 signaling has been shown to mediate differentiation for milk secretion." (PMID 38169886, 2023). "In breast cancer cells, the activation of ROBO1 signaling restrains tumorigenesis by blocking the PI3K/Akt/β-catenin pathway." (PMID 35615148, 2022). "In breast cancer progression is also involved circ-ROBO1 (has_circ_0124696), which promotes breast cancer-derived liver metastasis by sponging miR-217-5p, known to target Zeb1." (PMID 35626752, 2022). "The SLIT2/ROBO1 pathway inhibits cell invasion by interacting with E-cadherin and β-catenin in breast cancer and colorectal cancer, whereas in liver cancer, SLIT2/ROBO1 specifically inhibits hepatocyte growth factor (HGF)–mediated cell migration." (PMID 36498797, 2022). "In breast cancer, treatment with the anti-ROBO1 antibody reduces breast cancer-triggered angiogenesis and thereby retards cancer progression." (PMID 36277474, 2022). "A growing body of literature has shown that the activation of the Slit2/Robo1 axis can suppress the proliferation and invasion of multiple cancers, including cervical, colorectal and breast cancers." (PMID 33621954, 2021). "Meanwhile, ectopic Robo1 overexpression in breast cancer cells enhanced CAFs related tumor suppression effect." (PMID 33614646, 2021). "Stable Robo1-depletion in breast cancer cells abolished the CAFs tumor suppression effect in the orthotopic mouse model." (PMID 33614646, 2021). "Since Robo1 is known to have a tumor suppressor role in breast cancer biology, we next sought to determine if Robo1 has an epistatic interaction with Id loss of function using siRNA mediated knockdown of Robo1 followed by proliferation assays." (PMID 32766238, 2020). "CAF‐derived SLIT2 suppresses invasion of breast cancer cells expressing its receptor roundabout homolog 1 (ROBO1), through inhibition of PI3K and β‐catenin signaling." (PMID 29280568, 2018). "Previous observations suggest that ROBO1 can serve as a prognostic biomarker of breast cancer and brain metastasis." (PMID 29290962, 2017). "In this present study, we provided new evidence that Slit2/Robo1 axis is a suppressor of breast cancer progression." (PMID 26400100, 2015). "Recently, Slit2/Robo1 pathway has been demonstrated to be involved in the progression of breast carcinoma." (PMID 26400100, 2015). "To explore the prognostic significance of Slit2/Robo1 axis in breast cancer patients, we analyzed 118 IDC patients with complete clinical follow-up." (PMID 26400100, 2015). "Taken together, our studies demonstrate a novel role for Slit2/Robo1 axis in brain metastasis of breast cancer and probably provide a new therapeutic option in patients with brain metastasis." (PMID 26400100, 2015).
breast carcinoma (continued). "In this study, we investigated the correlation between Slit2/Robo1 signaling and breast cancer brain metastasis for the first time." (PMID 26400100, 2015). "The relationship between Slit2 or Robo1 expression and breast cancer brain metastasis was further investigated in an enlarged cohort of 33 IDC patients with brain metastasis and 110 IDC patients without brain metastasis." (PMID 26400100, 2015). "Overall, our findings indicated that Slit2/Robo1 axis possibly be regarded as a significant clinical parameter for predicting brain metastasis in breast cancer patients." (PMID 26400100, 2015). "The median interval from diagnosis of breast cancer to brain metastasis in patients with low expression of Robo1 (19 months) was much shorter than the high Robo1 expression group (38 months, Z = −2.720, P = 0.007)." (PMID 26400100, 2015). "In order to confirm the role of Slit2/Robo1 in breast cancer, we performed the migration assays in vitro." (PMID 26400100, 2015). "Next, we analyzed mRNA expression levels of Slit2 and Robo1 in gene expression profiling data sets from breast cancer and normal tissues." (PMID 26400100, 2015). "The validation data confirmed that mRNA expression levels of Slit2 and Robo1 were down-regulated in breast cancer tissues compared with their corresponding normal tissues (P < 0.01)." (PMID 26400100, 2015). "In lung cancer cells, USP33 interacted with Robo1, similar to the observation in the breast cancer cells, as detected by co-immunoprecipitation experiments." (PMID 24981056, 2014). "In contrast, Robo1 activity can promote glioma cell migration and metastasis of breast cancer cells to the brain." (PMID 21301049, 2010). "For instance, in breast carcinoma tissue samples, Robo1 has been shown to be over-expressed, and it has been demonstrated to induce migration of breast cancer cell lines." (PMID 20300657, 2010). "Slit2/Robo1 signaling can promote glioma cell migration and metastasis of breast cancer cells to the brain." (PMID 21301049, 2010). "In breast carcinoma tissue samples ROBO1 was shown to be overexpressed while SLIT2 induced migration of breast cancer cell lines." (PMID 19114000, 2008). "In humans, ROBO1 is located at 3p12 within a critical region of overlapping homozygous deletions in lung and breast cancers." (PMID 15534609, 2004). "Additionally, the other study revealed that overexpression of miR-29a inhibited cell migration and invasion by negatively regulating Robo1 (Roundabout 1) in breast cancer cells, highlighting the significant role of miR-29a in carcinogenesis breast cancer." (PMID 36140219, 2022). "MiR-218 represses invasion and migration of breast cancer cells by Slit2/Robo1 signaling." (PMID 33686957, 2021). "Besides, the research revealed that low expression of ROBO1 was exhibited worse prognosis in breast cancer patients, which was similar to our finding." (PMID 33134160, 2020). "Studies have found that low ROBO1 expression is an adverse prognostic factor for breast cancer and might play a role in the pathogenesis of colorectal cancer." (PMID 29698419, 2018). "We also contribute to ROBO1 findings on breast cancer research and on tumor biology." (PMID 29290962, 2017). "Therefore, we assumed that Slit2/Robo1 axis has effects on breast cancer brain metastasis probably by modulation of PI3K/Akt/β-catenin/MMP-9 signaling." (PMID 26400100, 2015). "In an earlier study, we demonstrated that there were no inactivating somatic mutations in ROBO1 in lung and breast cancers, but a CpG island in the 5′ region of ROBO1 was hypermethylated in breast and kidney tumours." (PMID 15534609, 2004). "Overexpression of ROBO1 has been shown in breast carcinoma tissue samples, and SLIT2 stimulates migration in breast cancer cell lines." (PMID 37238655, 2023). "Human melanoma and breast cancer cells expressing CXCR4, ROBO1, and ROBO2 are activated to migrate via CXCL12." (PMID 37238655, 2023).
breast carcinoma (continued). "Moreover, ROBO1 has been recognized as a tumor suppressor for various cancers, including breast cancer (BC)." (PMID 35054524, 2022). "Furthermore, the mean interval (from diagnosis of breast cancer to brain metastasis) and mean survival (from diagnosis of brain metastasis to death) were both significantly shorter in patients with low expression of Slit2 or Robo1 than the high expression group." (PMID 26400100, 2015). "CXCL12 was reported to activate the migration of human melanoma and breast cancer cells that express CXCR4, ROBO1 and ROBO2, while SLIT2-ROBO interaction was demonstrated to inhibit chemotaxis, chemoinvasion and adhesion of breast cancer cells." (PMID 19114000, 2008). "Further studies have demonstrated the absence of exon 2 in ROBO1 within cell lines of both lung and breast cancer." (PMID 37238655, 2023). "However, it was found that via downregulating Robo1, PRRG4 promoted breast cancer metastasis; thus, PRRG4 expression was found to be higher in breast tumors than in normal breast tissues." (PMID 38137332, 2023). "In this clinicopathologic study, we found that breast cancer patients with low expression of Slit2 or Robo1 exhibited brain-specific metastasis, but not liver, bone or lung." (PMID 26400100, 2015). "Moreover, low expression of Slit2 or Robo1 in breast cancer patients correlated with poor OS and DFS, suggesting Slit2/Robo1 axis can serve as a prognostic biomarker of breast cancer." (PMID 26400100, 2015). "In contrast, the activity of breast cancer cells lacking Robo1-expression was rather stimulated by Slit2-expressing fibroblasts, demonstrating that the functional outcome of CAF activity is decided on the level of the malignant cells." (PMID 24734219, 2014). "Notably, our clinical data showed, for the first time, that low expression of Slit2 or Robo1 positively correlated with brain-specific metastasis of breast cancer patients, but not liver, bone or lung metastasis." (PMID 26400100, 2015). "However, until present, there are no convincing reports that suggest whether the Slit2/Robo1 axis has any role in brain metastasis of breast cancer." (PMID 26400100, 2015). "In breast cancer cells, USP33 acts to redistribute Robo1 from the intracellular compartment to cell surface without affecting the total level of Robo1 protein." (PMID 24981056, 2014). "There was a negative correlation between ESR1 and ROBO1 in all BRCA, but positive in BRCA-Basal patients, indicating that ROBO1 could be a good complementary gene as a biomarker for breast cancer since there are few markers for BRCA-Basal cancer patients." (PMID 38137332, 2023).
dyslexia (38 papers, 2005 to 2025). A learning disorder characterized by an impairment in processing written words. "ROBO1 has well-established roles in brain development, and has been implicated in dyslexia as well as phonological short-term memory, while its homologue ROBO2 has been linked with expressive vocabulary during early language acquisition." (PMID 36794006, 2020). "ROBO1 itself is part of the immonoglobulin gene superfamily and is an axon guidance receptor gene previously implicated in dyslexia." (PMID 30557297, 2018). "For dyslexia susceptibility genes, the only gene for which there has been concordance between migration defects in RNAi and KO experiments is Robo1." (PMID 30218584, 2018). "Similar results have been found in experiments targeting homologs of the other main dyslexia susceptibility genes, Dyx1c1, Dcdc2, and Robo1." (PMID 29045729, 2017). "We found one novel intronic single nucleotide variant (SNV) and three novel intergenic SNVs in the broad region of ROBO1 that were specific to the dyslexia susceptibility haplotype." (PMID 26877820, 2016). "Further, candidate susceptibility genes for dyslexia (e.g., ROBO1) also appear to contribute to math difficulties." (PMID 27695426, 2016). "The ROBO1 gene that encodes an axon guidance receptor was found by identifying the breakpoints of a translocation, t(3;8; p12;q11), in a man with dyslexia and infertility." (PMID 23308072, 2012). "Although at least nine chromosomal loci are associated with dyslexia, for two of these loci the candidate genes were identified on the basis of a rare balanced chromosomal translocations disrupting ROBO1 and DYX1C1/EKN1." (PMID 22102821, 2011). "Because of its known function in neuronal axon guidance in the developing brain, ROBO1 was a plausible candidate gene for dyslexia susceptibility." (PMID 16254601, 2005). "Interestingly, another member of the roundabout gene family, roundabout guidance receptor 2 (ROBO2), is located near ROBO1 in a head-to-head orientation within the dyslexia susceptibility haplotype." (PMID 26877820, 2016). "ROBO1, implicated in communication disorder as dyslexia and communication disease." (PMID 26345457, 2015). "Mutations in ROBO1 cause speech sound disorders and dyslexia." (PMID 26107173, 2015). "Interestingly, similar to the ArKO mice, cortical disorganization, characterized by increased neuronal density was also observed in the brain of mice carrying a knockout of Robo1, another of the dyslexia-susceptibility genes (DYX5 locus)." (PMID 22426781, 2012). "For all of these genes, with the exception of ROBO1, associations with common single nucleotide polymorphisms (SNPs) have been reported suggesting that the genetic variants conferring susceptibility to dyslexia are found in the general population." (PMID 20846247, 2011). "SRGAP3 is a candidate for severe X-linked mental retardation and ROBO1 is a candidate for dyslexia." (PMID 20345892, 2010). "ROBO1 has been associated with dyslexia, a neurocognitive disorder of language and graphic processing that could be due to the abnormal migration and maturation of neurons during early development." (PMID 19468298, 2009). "Our data suggested that two functional copies of ROBO1 are required in brain development to acquire normal reading ability, and partial haplo-insufficiency for ROBO1 may predispose humans to specific dyslexia." (PMID 16254601, 2005). "As suggested by these findings, dyslexia may be caused in rare families by a small change in the expression of ROBO1, such as loss of one functional copy." (PMID 16254601, 2005). "Therefore, any of the new variants discovered in the dyslexia susceptibility haplotype may be of functional relevance to explain the reduced expression of the ROBO1 gene." (PMID 26877820, 2016). "Thus, ROBO1 is a candidate for a dyslexia susceptibility gene." (PMID 16254601, 2005).